MRPS10 (mitochondrial ribosomal protein S10)
Synonyms: MRP-S10; S10mt; FLJ10567; uS10m; PNAS-122
Tractability: Small molecule: a structure with a bound ligand is known. PROTAC: ubiquitination databases record sites on it; its protein half-life has been measured.
Gene: Protein-coding gene on chromosome 6 (42,206,694 to 42,217,881, reverse strand). Ensembl gene ENSG00000048544.
Subcellular location: Mitochondrion
Subcellular location (Human Protein Atlas): Mitochondria; Actin filaments
Pathways (Reactome):
Metabolism of proteins: Mitochondrial protein degradation; Mitochondrial ribosome-associated quality control; Mitochondrial translation elongation; Mitochondrial translation initiation; Mitochondrial translation termination
Gene Ontology:
Biological process: mitochondrial translation
Cellular component: mitochondrial small ribosomal subunit; mitochondrion; mitochondrial inner membrane; mitochondrial matrix
Genetic constraint (gnomAD): Loss-of-function variants: 18 observed, 19.98 expected, observed/expected ratio (o/e) 0.9, 90% interval 0.62 to 1.34. The upper end of that interval is the gene's LOEUF score, 1.34, which puts it in group 5 of 6, group 1 being the genes least tolerant of losing a copy. Missense variants: 202 observed, 186.57 expected, observed/expected ratio (o/e) 1.08, 90% interval 0.96 to 1.22. Synonymous variants: 73 observed, 70.09 expected, observed/expected ratio (o/e) 1.04, 90% interval 0.86 to 1.26.
Homologues: Orthologues: chimpanzee MRPS10 (99% identical), macaque GUCA1B (97% identical), pig MRPS10 (89% identical), rabbit MRPS10 (85% identical), mouse Mrps10 (82% identical), rat Mrps10 (79% identical), guinea pig MRPS10 (78% identical), tropical clawed frog mrps10 (55% identical), zebrafish mrps10 (50% identical), Drosophila melanogaster mRpS10 (35% identical), Caenorhabditis elegans mrps-10 (27% identical).
Diseases named in the same sentence as MRPS10 in open-access papers:
MRPS10 is named in the same sentence as 13 diseases in open-access papers, as found by Europe PMC text mining. Sharing a sentence is not in itself a finding about the gene and the disease. The quoted sentences say what the papers report.
breast carcinoma (3 papers, 2022 to 2024). "MRPS10, related to peptide chain elongation and mitochondrial translation, has been reported to be associated with various diseases such as breast cancer and rheumatoid arthritis." (PMID 38832038, 2024). "Mitochondrial ribosomal protein S10 (MRPS10), a 28S subunit protein belonging to the S10P ribosomal protein family, was found to be elevated in breast cancer, which might promote the fatty acid oxidation (FAO) process to support the rapid metabolism of tumor cells." (PMID 35892886, 2022).
AIDS (1 paper, 2015). A syndrome resulting from the acquired deficiency of cellular immunity caused by the human immunodeficiency virus (HIV). "Somewhat surprisingly, a lower transcription of MRPS10 but a higher transcription of MRPS7 are associated with slow and non-progression towards AIDS." (PMID 26367535, 2015).
Blindness (1 paper, 2021). Blindness is the condition of lacking visual perception defined as a profound reduction in visual perception. "For example, MRPL2, MRPL14, MRPS10, MRPS18A, and MRPS18B are candidate genes for spinocerebellar ataxia with blindness and deafness." (PMID 34987545, 2021).
chordoma (1 paper, 2023). Chordomas are rare malignant tumors arising from embryonic remnants of the notochord in axial skeleton. "Conversely, a small number of genes was identified whose gene dependency scores were of a greater magnitude in non-chordoma than in chordoma cell lines, and these genes included MED1, MRPS10, and DDX39B." (PMID 37024492, 2023).
Obesity (1 paper, 2024). Accumulation of substantial excess body fat. "Published studies have reported that MRPS10 was potentially related with diseases such as Cardiovascular disease and obesity." (PMID 38832038, 2024).
thyroid cancer (1 paper, 2023). "In a real-world experiment, the RT-qPCR results were consistent with the bioinformatic analysis, confirming that ADAMTSL4, DOCK6, FAM111B, and SEMA6B were expressed at higher levels in thyroid cancer cells (p < 0.05), while MRPS10 and PSMB7 were expressed at lower levels (p < 0.05)." (PMID 36761753, 2023).
tumor (2 papers, 2022 to 2023). "The validation part demonstrated that ADAMTSL4, DOCK6, FAM111B, and SEMA6B were expressed at higher levels in the tumor tissue, whereas lower expression of MRPS10 and PSMB7 was observed." (PMID 36761753, 2023).
MRPS10 also shares sentences with these, for which no sentence is quoted: cancer (1 paper); Cardiovascular disease (1); deafness (1); Hypertension (1); rheumatoid arthritis (1); spinocerebellar ataxia (1).